MRPL27 (mitochondrial ribosomal protein L27)
Synonyms: L27mt; bL27m
Tractability: Small molecule: a structure with a bound ligand is known. PROTAC: ubiquitination databases record sites on it; its protein half-life has been measured.
Gene: Protein-coding gene on chromosome 17 (50,367,857 to 50,373,207, reverse strand). Ensembl gene ENSG00000108826.
Subcellular location: Mitochondrion
Pathways (Reactome):
Metabolism of proteins: Mitochondrial ribosome-associated quality control; Mitochondrial translation elongation; Mitochondrial translation initiation; Mitochondrial translation termination
Gene Ontology:
Molecular function: protein binding; RNA binding; structural constituent of ribosome
Biological process: mitochondrial translation; translation
Cellular component: mitochondrial large ribosomal subunit; mitochondrion; mitochondrial inner membrane; ribosome
Genetic constraint (gnomAD): Loss-of-function variants: 4 observed, 14.7 expected, observed/expected ratio (o/e) 0.27, 90% interval 0.13 to 0.62. The upper end of that interval is the gene's LOEUF score, 0.62, which puts it in group 2 of 6, group 1 being the genes least tolerant of losing a copy. Missense variants: 196 observed, 204.38 expected, observed/expected ratio (o/e) 0.96, 90% interval 0.85 to 1.08. Synonymous variants: 82 observed, 79.58 expected, observed/expected ratio (o/e) 1.03, 90% interval 0.86 to 1.24.
Homologues: Orthologues: chimpanzee MRPL27 (99% identical), rabbit MRPL27 (84% identical), mouse Mrpl27 (83% identical), guinea pig MRPL27 (82% identical), rat Mrpl27 (78% identical), zebrafish mrpl27 (64% identical), tropical clawed frog mrpl27 (57% identical), dog MRPL27 (55% identical).
Diseases named in the same sentence as MRPL27 in open-access papers:
MRPL27 is named in the same sentence as 7 diseases in open-access papers, as found by Europe PMC text mining. Sharing a sentence is not in itself a finding about the gene and the disease. The quoted sentences say what the papers report.
cholangiocarcinoma (3 papers, 2021 to 2022). A carcinoma that arises from the intrahepatic biliary tree (intrahepatic cholangiocarcinoma) or from the junction, or adjacent to the junction, of the right and left hepatic ducts (hilar cholangiocarcinoma). "After adjusted these indicators, MRPL27 and vascular invasion were risk factors for OS in cholangiocarcinoma patients in multivariate model (HR = 4.99, p = 0.038 and HR = 11.13, p = 0.007, respectively)." (PMID 33456351, 2021). "After adjusting surgical procedure, vascular invasion and new tumor event after original treatment, MRPL27 was identified as independent risk factor for DFS in cholangiocarcinoma patients (HR = 5.72, p = 0.013)." (PMID 33456351, 2021). "Cox regression models were used to evaluate the potential links between MRPL27 and cholangiocarcinoma survival." (PMID 33456351, 2021). "MRPL27 protein was low stained in three normal liver tissues, while medium stained in two of four cholangiocarcinoma tissues." (PMID 33456351, 2021). "Cholangiocarcinoma patients with high MRPL27 had worse overall survival (OS) and disease-free survival (DFS) compared to those with low MRPL27 (all p < 0.05)." (PMID 33456351, 2021). "In GEPIA online service, 36 cholangiocarcinoma patients were divided into MRPL27 high and low expression groups by median cutoff." (PMID 33456351, 2021). "Univariate and multivariate Cox models indicated that MRPL27 should be a risk factor for the OS and DFS in cholangiocarcinoma patients (both p < 0.01)." (PMID 33456351, 2021). "MRPL27 mRNA was significantly upregulated in tumor tissues compared to adjacent normal tissues in cholangiocarcinoma patients (p = 0.003)." (PMID 33456351, 2021). "MRPL27 mRNA was significantly upregulated in tumor tissues in cholangiocarcinoma patients including intrahepatic, distal and hilar/perihilar cholangiocarcinoma cases (all p < 0.01)." (PMID 33456351, 2021). "MRPS12 is a potential oncogene of ovarian cancer, while MRPL27 displays an adverse effect on the overall survival rate and disease-free survival rate of cholangiocarcinoma patients." (PMID 34868337, 2021). "Cholangiocarcinoma patients with high MRPL27 in tumor tissues had significantly worse OS and DFS compared to those with low MRPL27 levels (HR = 4.6, p = 0.004 and HR = 6.1, p < 0.001, respectively)." (PMID 33456351, 2021). "A study of 36 patients with cholangiocarcinoma demonstrated that MRPL27 mRNA levels are significantly upregulated in tumor tissues, and patients with high MRPL27 expression had a poorer overall survival and disease-free survival than those of patients with low MRPL27 expression." (PMID 35719986, 2022). "Secondly, we could not conduct experimental research for probing potential oncogenic mechanisms of MRPL27 in cholangiocarcinoma development." (PMID 33456351, 2021). "Taken together, we speculated that MRPL27 might be a potential candidate target for cancer therapy including cholangiocarcinoma." (PMID 33456351, 2021). "In addition, we compared the baseline characteristics of cholangiocarcinoma patients between MRPL27 high and low expression groups." (PMID 33456351, 2021). "As member of ribosome pathway, MRPL27 might contribute to the carcinogenesis progression in human cancers including cholangiocarcinoma." (PMID 33456351, 2021). "In addition, no mutations of MRPL27 were identified in cholangiocarcinoma patients via screening in cBioPortal for cancer genomics." (PMID 33456351, 2021). "MRPL27, surgical procedure, AJCC stage, vascular invasion, perineural invasion and new tumor event after original treatment might potential factors associated with OS in cholangiocarcinoma patients (p < 0.10)." (PMID 33456351, 2021). "No mutations of MRPL27 were screened in cholangiocarcinoma patients." (PMID 33456351, 2021). "According to our preliminary findings, we cautiously concluded that upregulation of MRPL27 in tumor tissues predicted worse OS and DFS in cholangiocarcinoma patients." (PMID 33456351, 2021).
cholangiocarcinoma (continued). "MRPL27, surgical procedure, vascular invasion and new tumor event after original treatment were potential indicators for DFS in cholangiocarcinoma patients (p < 0.10)." (PMID 33456351, 2021). "Additionally, no mutations of MRPL27 were screened in cholangiocarcinoma patients in our research." (PMID 33456351, 2021). "In validation set, Kaplan-Meier method revealed that high level of MRPL27 in tumor tissues contributed to poorer OS and DFS in cholangiocarcinoma patients (p = 0.022 and p = 0.02, respectively)." (PMID 33456351, 2021). "However, no study has focused on the oncogenic roles of MRPL27 in cholangiocarcinoma." (PMID 33456351, 2021).
intrahepatic cholangiocarcinoma (1 paper, 2021). A carcinoma that arises from the intrahepatic bile duct epithelium in any site of the intrahepatic biliary tree. "According to the tumor locations, MRPL27 mRNA was significantly overexpression in tumor tissues in intrahepatic cholangiocarcinoma, distal cholangiocarcinoma and hilar/perihilar cholangiocarcinoma patients (p = 0.003, p = 0.004 and p < 0.001, respectively)." (PMID 33456351, 2021).
tumor (2 papers, 2021 to 2022). "Our bioinformatic analysis also indicated that MRPL27 contributed to ATP synthesis, which together with oxidative phosphorylation might involve in the tumor energy support system and contribute to cancer aggressiveness." (PMID 33456351, 2021).
MRPL27 also shares sentences with these, for which no sentence is quoted: cancer (1 paper); metabolic syndrome (1); ovarian carcinoma (1); perihilar cholangiocarcinoma (1).